BMP2 (bone morphogenetic protein 2)
Diseases named in the same sentence as BMP2 in open-access papers (continued):
Sharing a sentence is not in itself a finding about the gene and the disease.
myopia (continued). "In this study, we aim to clarify the role of BMPs (BMP-2, −4, and −5) by examining any changes during myopia induction in guinea pigs sclera, and in vitro the effect of BMPs on sclera fibroblasts differentiation, ECM, and its potential signal pathway." (PMID 21403850, 2011). "It was found that the expression of BMP2 was downregulated in animal models of myopia." (PMID 40375931, 2025). "However, evidence during the past decade has demonstrated adverse side-effects of BMP-2, such as hematoma formation, osteolysis, increased spontaneous fractures, coronary artery disease, myopia, and other complications." (PMID 32933207, 2020). "However, overexpression of BMP-2 can lead to early myopia, and thus, its activity must be tightly regulated during embryogenesis and throughout development." (PMID 32933207, 2020). "Notably only one gene, BMP2, was differentially expressed during both myopia and hyperopia induction in a sign-of-defocus dependent manner." (PMID 27625591, 2016). "Genetic analyses have suggested that BMP2 is a myopia-related gene." (PMID 25965995, 2015). "Therefore, we investigated the link of BMP-2 to the regulation of ECM synthesis in the sclera of eyes developing myopia." (PMID 25965995, 2015). "Our results suggest that BMP-2 may influence extracellular matrix synthesis and scleral reconstruction, which contributes to the development of human myopia." (PMID 19098993, 2008). "All these suggested that BMP-2 may act as a cytokine in the control of scleral extracellular matrix remodeling in myopia progression." (PMID 19098993, 2008). "A gene microarray analysis was used to identify gene expression changes in human scleral fibroblasts in response to mechanical loads and possible mechanisms of scleral remodeling in the development of myopia and showed that mechanical stresses induced BMP-2 mRNA expression after 30 min and 24 h." (PMID 19098993, 2008). "In addition, over-expression of BMP-2 can lead to myopia or neural tube closure defects." (PMID 32933207, 2020). "Our data suggest that BMP-2 could influence fibroblast proliferation and differentiation as well as extracellular matrix synthesis, which contributes to the development of human myopia." (PMID 21403850, 2011). "Based on these studies, BMP-2 and BMP-5 are assumed to be involved in the development of myopia and their expression is seen to decrease during this process." (PMID 40696418, 2025). "On the other hand, BMP-2 can elevate the level of TIMP-2 to diminish MMP-2 activity of degradation for collagen and GAGs, thereby delaying the progression of myopia." (PMID 40696418, 2025). "We observed downregulation of BMP2 and BMP4 in chick myopia, similar to previous studies, and these genes are also implicated in human myopia." (PMID 39876870, 2024). "In this study, we examined three gene expression changes in Bmp2, Id3, and Nog in RPE during myopia induction and subsequent recovery from myopia." (PMID 37759773, 2023). "In our study, the BMP-2 expression profile in LIM was decreased and when the myopia regressed, its expression also recovered, so this provides further information about the possible role of BMP-2 in ocular growth and scleral remodeling in myopia." (PMID 25965995, 2015). "In summary, this study demonstrates that scleral BMP-2 expression is reduced in myopia development and that BMP-2 may be involved in scleral ECM remodeling in myopia." (PMID 25965995, 2015). "This study investigated bone morphogenetic protein-2 (BMP-2) expression in the sclera of guinea pigs with lens-induced myopia (LIM) and after recovery from myopia and evaluated the effect of BMP-2 on extracellular matrix (ECM) synthesis in human scleral fibroblasts (HSFs) cultured in vitro." (PMID 25965995, 2015). "In addition, BMP-2 was reduced in the posterior sclera of FDM guinea pigs, which further indicates that BMP-2 influenced ECM and scleral reconstruction in progress of human myopia." (PMID 26967733, 2016).
myopia (continued). "Overall, there appears to be a tight, albeit inverse relationship between the directions of AL and BMP2 gene expression changes, with ID3 gene expression changes mirroring BMP2 gene expression changes during myopia induction but not during recovery from the same treatment." (PMID 37759773, 2023).
craniosynostosis (16 papers, 2015 to 2025). Craniosynostosis is defined as the premature fusion of one or more cranial sutures leading to secondary distortion of skull shape resulting in skull deformities with a variable presentation. "In fact, GWASs on non-syndromic craniosynostosis have identified risk SNPs near BMP2, BMP7, BMPER, and DLX5, which overlap with loci identified here, and are directly linked to RUNX26,111–115." (PMID 40087503, 2025). "Recent reports focusing on patients with non-syndromic craniosynostosis showed that single nucleotide polymorphisms (SNPs) were found in a Smad6 exon and a putative enhancer region of BMP2, and frameshift mutations in Smad6 were found." (PMID 37275223, 2023). "The first GWAS on craniosynostosis identified susceptibility loci for non-syndromic sagittal craniosynostosis near bone morphogenetic protein-2 (BMP2) and within Bardet-Biedl syndrome 9 (BBS9)." (PMID 35451466, 2022). "A previous study identified rare SMAD6 and common BMP2 alleles involved with craniosynostosis in humans." (PMID 34539446, 2021). "This was typically because one parent had only the SMAD6 mutation while the other had only the common BMP2 variant; the transmission of both to their offspring resulted in craniosynostosis." (PMID 27606499, 2016). "Rare damaging variants in SMAD6 alone impart very large effects on disease risk with low penetrance, with inheritance at BMP2 explaining nearly all of the variation in occurrence of craniosynostosis seen among SMAD6 mutation carriers." (PMID 27606499, 2016). "This search revealed that rare mutations that disable one copy of a gene called SMAD6 in combination with a common DNA variant near another gene called BMP2 account for about 7% of infants with midline forms of craniosynostosis." (PMID 27606499, 2016). "Lastly, we compared the joint segregation of rare damaging SMAD6 and common BMP2 risk alleles to the segregation of craniosynostosis in a parametric two locus linkage model in these kindreds." (PMID 27606499, 2016). "Furthermore, in identifying the role of disease-modifying genes associated with craniosynostosis, a genome-wide association study (GWAS) has spotted susceptibility loci close to bone morphogenetic protein-2 (BMP-2) in sagittal nonsyndromic craniosynostosis." (PMID 38910614, 2024). "While nonsyndromic craniosynostosis common-variant GWASs have had less statistical power for variant discovery due to their smaller sample sizes, variants at the BMP2 locus have been independently associated with two main subtypes, sagittal and metopic craniosynostosis." (PMID 35483406, 2022). "Interestingly, this allele, p.E287K, (ExAC frequency 3.3 × 10–5) was transmitted to a proband with sagittal and metopic craniosynostosis along with two doses of the BMP2 risk allele, each inherited from a heterozygous parent." (PMID 27606499, 2016). "However, when an individual has both the SMAD6 mutation and the BMP2 risk allele (which on its own leads to the disorder in just 0.08% of cases), craniosynostosis occurs 100% of the time." (PMID 27687826, 2016). "Genotypes of a common variant near BMP2 that is strongly associated with midline craniosynostosis explained nearly all the phenotypic variation in these kindreds, with highly significant evidence of genetic interaction between these loci via both association and analysis of linkage." (PMID 27606499, 2016). "GWAS has also identified BMP2 and BMP7 as susceptibility loci for craniosynostosis, further implicating this pathway as an important regulator of suture closure and craniosynostosis." (PMID 38385025, 2024). "While our functional studies focused on genes uniquely associated with variation in skull BMD, there are plenty of genes implicated in craniosynostosis (e.g., EN1, RUNX2, SOX6, BMP2, JAG1, LRP5, IDUA30,44,47,48) across the whole set of identified BMD loci." (PMID 37402774, 2023).
craniosynostosis (continued). "More complex presentations are well-characterized by the discovery of a two-loci inheritance resulting in midline craniosynostosis, involving interaction between rare coding variants in SMAD6 and the risk allele of rs1884302 in the vicinity of BMP2, finding that has been replicated." (PMID 36225206, 2022). "SMAD6 mutations with and without BMP2 risk alleles account for ~7% of probands in this cohort of non-syndromic midline craniosynostosis." (PMID 27606499, 2016). "A previous GWAS of non-syndromic sagittal craniosynostosis implicated common variants ~345 kb downstream of the closest gene, BMP2 (encoding bone morphogenetic protein 2), with unusually large effect size (e.g., rs1884302, with risk allele frequency of 0.34 and odds ratio of 4.6)." (PMID 27606499, 2016). "Epistatic interactions have been described for cystic fibrosis (CFTR) and DCNT4 or craniosynostosis (SMAD6) and BMP2 amongst others." (PMID 37477760, 2023). "The combination of a rare damaging SMAD6 mutation plus a common BMP2 risk allele conferred 100% risk of craniosynostosis in our cohort, while those with a SMAD6 mutation but no BMP2 risk allele were at markedly lower risk." (PMID 27606499, 2016). "Many of the variants in BMP signaling components (e.g., SMAD6, BMP2, BMP7) increase the risk of craniosynostosis rather than causing craniosynostosis directly, suggesting that interactions between pathways (namely, BMP and FGF) may contribute to the etiology of this disorder." (PMID 38385025, 2024).
melanoma (16 papers, 2010 to 2026). A malignant, usually aggressive tumor composed of atypical, neoplastic melanocytes. "Expression analysis of BMP2 reveals that both primary and metastatic melanomas with poorer survival showed lower expression levels of BMP2, while higher expression was associated with improved survival favouring an anti‐tumoral effect in melanomas." (PMID 40135438, 2025). "Therapeutical inhibition of BMP2 activity reduces invasive phenotypes and sensitizes melanomas to BRAF/MEK inhibition." (PMID 41470117, 2025). "Ageing in fibroblasts induced Enhancer of zeste homolog 2 (EZH2) decline and increased Bone Morphogenetic Protein 2 (BMP2) secretion, these mechanisms induce slower-cycling, highly invasive and therapy-resistant melanomas." (PMID 41470117, 2025). "Skin reconstructs with untreated, BMP-2- and nodal pre-treated melanoma aggregates depicted similar images: proliferating, massively invasive, growing primary tumors completely penetrating the entire extension of the skin reconstructs." (PMID 29716947, 2018). "Here, we show that BMP-2 is highly expressed in invasive melanoma cells and is elevated in the serum of stage IV melanoma patients compared to stage IB-IIC patients and healthy controls." (PMID 29716947, 2018). "Direct activation of SMAD2 and SMAD3 by ALK3 has been demonstrated in BMP2-treated melanoma and pituitary gonadotrope cells, respectively." (PMID 29416020, 2018). "In the current study we observed a high BMP-2 expression in melanoma cells with an invasive phenotype." (PMID 29716947, 2018). "For the following experiment we used pre-existing histological slides of our chick embryo model and correlated single melanoma cell invasion in the rhombencephalon of the chick embryo with BMP-2 RNA-expression of the corresponding melanoma cell line." (PMID 29716947, 2018). "Our RNAseq analysis revealed that a subset of melanoma cells from patients under MAPK-inhibition had a strong expression of BMP-2 when compared to therapy-naïve patients (median 0.48 vs 4.10 counts per million, P=0.06, t-test)." (PMID 29716947, 2018). "Together, an increased serum BMP-2 level correlates with short survival in stage IV melanoma patients." (PMID 29716947, 2018). "Highly BMP-2-expressing melanoma cells display enhanced invasion in the rhombencephalon of the chick embryo." (PMID 29716947, 2018). "The capability to resume neural crest cell migration depends on the constitutive production of BMP-2 (bone morphogenetic protein-2) and can be ablated by pre-treatment of melanoma cells with the embryonic BMP antagonist noggin." (PMID 23342051, 2013). "This demonstrates that BMP-2 up-regulation is a general phenomenon in invasive melanoma cells." (PMID 29716947, 2018). "BMP-2 is up-regulated in invasive melanoma cells and is a known inducer of EMT." (PMID 29716947, 2018). "We therefore reasoned that neural crest migration and malignant invasion of melanoma cells could also be BMP-2-dependent." (PMID 29716947, 2018). "In a second approach, we asked whether BMP-2 or nodal might be involved in the transition of radial growth phase (RGP) melanoma cells to a vertical/invasive growth phase (VGP)." (PMID 29716947, 2018). "Therefore we measured the BMP-2 concentration in serum samples of controls and melanoma patients and analyzed the role of BMP and nodal for physiological neural crest migration in the zebrafish embryo." (PMID 29716947, 2018). "We previously demonstrated that the BMP-antagonist noggin blocked the EMT phenotype of melanoma cells in the neural crest and malignant invasion of melanoma cells in the chick embryo; vice-versa, malignant invasion was induced in human melanocytes in vivo by pre-treatment with BMP-2." (PMID 29454361, 2018).
melanoma (continued). "Interestingly, in the control, BMP-2 and nodal groups, the invading melanoma cells depicted a mesenchymal, stretched morphology, while in the antagonist groups, clusters of epithelial-like, rounded, aggregated BLM cells prevailed in the dermal part of the skin reconstructs." (PMID 29716947, 2018). "In addition to BMP-2, melanoma cells constitutively express the TGFbeta-family member nodal." (PMID 29716947, 2018). "Melanoma inhibitory activity (MIA) affects the differentiation to hyaline cartilage and can inhibit the osteogenic potential of bone morphogenetic protein (BMP)-2 in mesenchymal stem cells (MSC)." (PMID 28704392, 2017). "RT‐PCR analysis of melanoma cell lines A375 and A375 MEK after treatment with IC50 concentrations of KU757 confirmed the downregulation of CD20, CD25 and NDUFA7, as well as the upregulation of PRKCH, BMP2 and ADAMTS9 hub genes (p < 0.05)." (PMID 40135438, 2025). "Also, BMP‐2 and ‐4 stimulation of primary human fibroblast led to MMP‐1, ‐2, ‐3, and ‐13 upregulation which was suggested to be a mechanism in melanoma invasion." (PMID 33629769, 2021). "The importance of BMP for melanoma cell invasion was further supported by the observation that BMP-2 induced invasion of non-transformed human melanocytes in the optic cup as ectopic site of the chick embryo." (PMID 29716947, 2018). "In addition to driving neural crest migration in the zebrafish embryo, the agonists BMP-2, BMP-7 and nodal induce EMT/invasion in radial growth phase melanoma cells and in human melanocytes in skin reconstructs." (PMID 29716947, 2018). "In contrast to melanoma cells, neurospheres generated from adult mouse subventricular zone (SVZ) stem cells integrate into the neural crest and perform neural crest cell migration only after pre-treatment with bone morphogenetic protein-2 (BMP-2)." (PMID 29454361, 2018). "Together, these data show that BMP-2, nodal and their respective antagonists neither influence melanoma cell proliferation nor sensitize melanoma cells for the current standard treatment regimen for BRAF-mutated metastatic melanoma patients (BRAF±MEK-inhibition)." (PMID 29716947, 2018). "To assess the possible influence of the agonists BMP-2 and nodal, their antagonists noggin and lefty and the nodal receptor antagonist SB431542 on cell proliferation, we conducted cell cycle analyses of B16F1, 451LU and SKMEL28 melanoma cells after treatment with agonists or antagonists." (PMID 29716947, 2018).
Obesity (16 papers, 2011 to 2025). Accumulation of substantial excess body fat. "This study provides evidence that CXCL-16, IL-17, and BMP-2 are potential plasma indicators of inflammatory status in middle-aged and elderly women; therefore, further investigation of obesity-related comorbidities is recommended." (PMID 28293269, 2017). "Thus, the aim of the present study was to investigate the association between CXCL-16, BMP-2, and IL-17 plasma levels and overweight and obese conditions in middle-aged (35 to 55 years of age) and elderly (>60 years old) women to find possible targets to monitor early progression to obesity." (PMID 28293269, 2017). "Of importance, these parameters were notably decreased whereas the anti-fibrotic biomarkers (the protein expressions of BMP-2 and p-Smad1/5) were significantly increased in mice after reduction in obesity." (PMID 22784636, 2012). "BMPs are important regulators of adipogenesis and may play a role in obesity, and increases in BMP2 expression may contribute to the partitioning of energy storage into visceral and subcutaneous adipose tissue depots." (PMID 33942864, 2021). "BMP-2 has been shown to promote osteogenic differentiation and adipogenesis in bone marrow stromal cells, and it could be partially responsible for increased obesity." (PMID 28293269, 2017). "Consistent with recent studies on BMPR1A, positive correlation of BMPR2 mRNA expression with obesity suggests that obese individuals may have enhanced BMP-2/4 signalling, which may stimulate adipose tissue differentiation thereby contributing to increased fat mass." (PMID 21311592, 2011). "Our analysis suggested significant enrichment (corrected P‐value < 0.01) in various catalogs, including obesity‐related traits (e.g., GMDS, PRKG1, and BMP2), Height (e.g., IGF2BP3, BMP2, and BMP3), and Body mass index (e.g., BMP2)." (PMID 40167159, 2025). "BMP2 expression in both VAT and SAT was significantly higher in people with obesity when compared with individuals who were healthy and lean." (PMID 34258293, 2021). "BMP2, BMP4, BMP6, BMP7, and BMP9 have been shown to affect the pathophysiological process of obesity and glucose metabolism beyond bone metabolism." (PMID 34258293, 2021). "Eight genes (BCAT1, BMP2 K, CSRNP2, MYNN, NCKAP5L, SAP30BP, SLC35B4, and SP1) were isolated as candidates for obesity." (PMID 24455749, 2013). "Overall, BMPs, mainly including BMP9, BMP4, BMP2, and BMP7, may exert functions both in bone and in obesity as well as glucose metabolism." (PMID 34258293, 2021). "The rest of the candidates, C2orf15, DENND1B, MRPL30, POC1B, RP4-655J12.3, TMBIM4, BMP2 K, CSRNP2, NCKAP5L, TOMM5, and BAP1, may be novel genes related to T2DM or obesity." (PMID 24455749, 2013). "The expressions of fibrotic markers phosphorylated Smad3 and TGF-β were higher, whereas expression of anti-fibrotic phosphorylated Smad1/5 and BMP-2 were lower (all p<0.02); and LVEF was lower, whereas the LV remodeling was higher in obesity than in control and OR (all p<0.001)." (PMID 22784636, 2012).